NORAD (non-coding RNA activated by DNA damage)
Diseases named in the same sentence as NORAD in open-access papers (continued):
Sharing a sentence is not in itself a finding about the gene and the disease.
tumor (continued). "PCNA is a key medium in the process of DNA replication and can be used as a proliferation marker to evaluate the cell proliferation of xenograft tumor cells.These data indicated that NORAD regulated cell malignant behaviors via sponging miR-495-3p in PCa." (PMID 32694945, 2020). "While introduction of NORAD-4 fragment significantly impaired the tumor growth and cell apoptosis inhibition mediated by knockdown of NORAD in vivo." (PMID 32555178, 2020). "And NORAD was downregulated in mice tumor tissues of the sh-NORAD group compared to the control group, and NORAD expression in mice tumor tissues of the sh-NORAD + anti-miR-495-3p group was consistent with the sh-NORAD group." (PMID 32694945, 2020). "In our study, the expression level of NORAD was significantly upregulated in the PC tumor tissues compared with adjacent normal tissues." (PMID 33292272, 2020). "For example, by interacting with miRNAs, several lncRNAs (including GAS5, XIST, NORAD, and Linc00511) modulate PC progression by enhancing the proliferation, migration and invasive capacity and angiogenesis of PC cells as well as tumor growth in vivo." (PMID 31488171, 2019). "Notably, our study reveals that lncRNA NORAD in EVs promotes NSCLC tumor growth through the miR-520g-3p axis in vivo." (PMID 39215037, 2024). "Furthermore, lncRNA NORAD in EVs derived from M2 macrophages is found to promote NSCLC tumor growth through the miR-520g-3p axis in vivo." (PMID 39215037, 2024). "Moreover, NORAD was negatively correlated with the presence of CD8 T-cells, cytotoxic lymphocytes and T-cells in the tumor, while it was positively associated with the levels of fibroblasts, endothelial cells and neutrophils." (PMID 38339387, 2024). "In the human HCC70 BC cell line, NORAD seems to work as a tumor suppressor through its capability to sponge miR155-5p, which leads to the positive regulation of SOCS1 and a reduction in cell proliferation, migration and invasion behavior in vitro, affecting overall BC progression." (PMID 38339387, 2024). "Furthermore, the impact of M2 macrophage-derived lncRNA NORAD in EVs on tumor growth was confirmed using xenograft tumor animal models." (PMID 39215037, 2024). "Considering the correlation between NORAD and genome instability, as well as the contradictory effect of chromosomal instability in tumor progression, we investigate whether targeting NORAD could act synergistically with cytotoxic agents." (PMID 37680988, 2023). "LncRNAs such as MALAT1, XIST and NORAD have been proven to be biomarkers for human tumor prognosis." (PMID 35183058, 2022). "In addition, NORAD levels were significantly increased in dox-treated C42/miR-346 xenografts as compared to untreated tumours (Fig S14Eii), potentially illustrative of NORAD upregulation as an adaptive response to chronic miR-346 expression." (PMID 35317841, 2022). "More importantly, xenograft and lung metastasis models were constructed, and it was confirmed that NORAD-sponged miR-378c blocked STAD tumor growth and metastasis in vivo through inhibiting miR-378c, which was supported by the loss of tumor weight, volume and metastatic number." (PMID 35164743, 2022). "Importantly, miR-346 sensitises PC cells to DNA-damaging drugs including PARP inhibitor and chemotherapy, and induces tumour regression as a monotherapy in vivo, indicating that targeting miR-346:NORAD balance is a valid therapeutic strategy." (PMID 35317841, 2022). "Tumor growth was monitored, and it was found that miR-378c-agomir-induced loss of tumor volume and weight was partly rescued by NRP1 or NORAD overexpression." (PMID 35164743, 2022). "In addition, the in vivo experiments showed increased tumor growth and weight in nude mice administered with EVs and decreased tumor growth and weight in nude mice administered with EVs-si-NORAD." (PMID 35281474, 2022). "In the context of tumor phenotypes, NORAD may be acting in different ways between the two subtypes and may present a tumor suppressor or oncogenic role." (PMID 36412911, 2022).
tumor (continued). "Mechanically, NORAD might function as a competing endogenous RNA to regulate miR-202-5p, which acts as a tumor-suppressor via the TGF-β pathway." (PMID 35682549, 2022). "In the context of tumor phenotype, NORAD may act differently between the two subtypes and may present a tumor suppressor or oncogenic role." (PMID 36412911, 2022). "Interestingly, NORAD knockdown also enhances the efficacy of immune checkpoint inhibitors in combination with radiotherapy in tumour treatment." (PMID 34587992, 2021). "However, much remains to be learned about the effects and biological mechanisms of NORAD in PC According to recent research, miR-202-5p acts as a tumor-suppressor in the context of breast cancer and colorectal carcinoma." (PMID 34551785, 2021). "Furthermore, KYSE30 cells pretreated with the NORAD overexpression vector formed continuously growing tumours even when they were treated with CDDP." (PMID 34893064, 2021). "Similarly, the expressions of MTDH in xenograft tumours derived from KYSE30 cells with NORAD overexpression were higher than those cells with EV." (PMID 34893064, 2021). "The data presented above indicate up-regulation of NORAD in almost all types of neoplasm." (PMID 34485302, 2021). "Knockdown of NORAD resulted in excessive tumor growth and reduced apoptosis." (PMID 32555178, 2020). "Collectively, these results manifested that NORAD inhibition could constrain tumor growth in vivo through the miR-495-3p/TRIP13 axis." (PMID 32694945, 2020). "Furthermore, NORAD inhibition reduced tumor growth in vivo, while this decrease was partly abolished by miR-495-3p inhibitor." (PMID 32694945, 2020). "While, both exogenous NORAD overexpression and rescued endogenous NORAD expression by Aza could inhibit cell growth and promote cell apoptosis, as a tumor suppressor." (PMID 32555178, 2020). "NORAD could promote EC cell apoptosis in vitro and knockdown of NORAD resulted in tumor malignant growth in vivo." (PMID 32555178, 2020). "Based on the observed regulatory effect between NORAD and miR‐205, we further investigated whether NORAD mediated the inhibitory effects of miR‐205 knockdown in tumor migration and invasion." (PMID 30843652, 2019). "NORAD is implicated in various aspects of carcinogenesis, encompassing proliferation, invasion, metastasis and apoptosis, mediated by multiple mechanisms and signaling pathways, including inducing epithelial-to-mesenchymal transition (EMT) and sponging tumor-associated miRNAs." (PMID 38791575, 2024). "Thus, we judged that NORAD was a tumor promoter in OSCC cells." (PMID 34991683, 2022). "Thus, NORAD has a tumor-promoting effect in HCC, likely through sequestering miR-202." (PMID 35682549, 2022). "Knockdown of NORAD could promote tumor growth and prevent cell apoptosis in vitro and in vivo." (PMID 32555178, 2020). "Moreover, knockdown of NORAD promoted tumor growth in the xenograft mice model." (PMID 32555178, 2020). "In this way, NORAD promotes BC progression by regulating the TGF-β signaling pathway, highlighting the potential control of NORAD as a key tumor-suppressive event in BC." (PMID 38339387, 2024). "To investigate the potential role of NORAD in BRCA cells, we examined its expression in CSL knockout (KO) xenograft tumor models." (PMID 37993524, 2023). "NORAD enhances the expression of the oncogenic HDAC8 by acting as a miR‐144‐3p sponge, thereby stimulating tumour cell proliferation, metastasis and resistance to DOX, while concurrently suppressing apoptosis and autophagy." (PMID 37837401, 2023). "NORAD acts as a sponge for miR‐433‐3p, upregulating the expression of downstream target genes ATG5 and ATG12 to increase autophagic flux and improve tumour cell resistance to L‐OHP." (PMID 37837401, 2023). "For example, the lncRNA, NORAD, is upregulated in non-small cell lung cancer (NSCLC) and accelerates the progression of NSCLC by enhancing tumor cell proliferation by targeting the miRNA-455/CDK14 axis." (PMID 36793900, 2023).
tumor (continued). "Further experiments showed that continuous exposure to L‐OHP induces DNA damage repair responses in tumor cells, activating CREBBP in the NORAD promoter region and inducing H3K27ac, leading to upregulation of NORAD expression." (PMID 37837401, 2023). "Significantly, regulation of NORAD affects the PUM proteins and changes the extracellular vesicle (EV) proteins that participate in communication between cells in the tumor microenvironment." (PMID 36514044, 2022). "Overall, it was validated that miR-378c inhibited tumor growth and lung metastasis of STAD in vivo through mediating NORAD/NRP1 axis." (PMID 35164743, 2022). "Therefore, NORAD may serve as an oncogenic target for tumor angiogenesis in CRC." (PMID 34969360, 2022). "NORAD promoted cell proliferation, invasion and EMT via the miR-30a-5p/RAB11A/WNT/β-catenin pathway, thus inducing PC tumor growth." (PMID 33292272, 2020). "Moreover, we detected the expression levels of NORAD and miR-30a-5p in the tumors obtained from the mice subcutaneously injected with the transfected cells, and the results indicated NORAD was downregulated and miR-30a-5p was increased in the tumor tissues of nude mice in each group." (PMID 33292272, 2020). "Silenced NORAD expression decreased the levels of cyclinD1 and PCNA in mice tumor tissues, but this reduced overturned by miR-495-3p silencing." (PMID 32694945, 2020). "While, introduction of NORAD-4 fragment, which bound with FUBP1, successfully reversed tumor growth and apoptosis inhibition mediated by NORAD knockdown in vivo." (PMID 32555178, 2020). "In the present study, we demonstrated that the lncRNA NORAD is upregulated during hypoxia and promotes EMT in tumor cells." (PMID 29121972, 2017). "Notably, lncRNA NORAD in EVs promoted NSCLC cell proliferation, and promoted NSCLC tumor growth through the miR-520g-3p axis." (PMID 39215037, 2024). "Notably, lncRNA NORAD in EVs promoted the proliferation of NSCLC cells and facilitated NSCLC tumor growth through the miR-520g-3p axis." (PMID 39215037, 2024). "Notably, lncRNA NORAD in EVs in EVs promoted NSCLC cell proliferation, as well as NSCLC tumor growth through the miR-520g-3p axis." (PMID 39215037, 2024). "In addition, the correlation between serum NORAD expression and various clinicopathological characteristics of BRCA, such as age, TNM-stage, tumor size, lymph node metastasis, and luminal classification, was investigated." (PMID 37993524, 2023). "The signature of NORAD and RALGAPB in Lum A and Basal-like subtypes can predict a worse or better prognosis according to the survival of patients, and also has the potential to discriminate tumor and non-tumor groups." (PMID 36412911, 2022). "Moreover, NORAD knockdown inhibits CRC cell proliferation, migration, tumor growth, and stem-like cell invasion." (PMID 34969360, 2022). "NORAD knockdown significantly sensitized tumours to radiation, but anti-PD-1 monotherapy was not sufficient to control tumour growth." (PMID 34587992, 2021). "Similarly, Western blotting assay suggested miR-30a-5p inhibitor partially eliminated the suppressive effect of NORAD siRNA on the WNT pathway, thus inhibiting the tumor growth." (PMID 33292272, 2020). "The expression of NORAD was also upregulated in most tumor tissues compared with the non-tumor tissues from the same donor, thus linking the upregulation of NORAD to pathological changes in pancreatic tissue." (PMID 29121972, 2017). "Furthermore, expressions of NORAD and CREBBP were augmented while miR-877-3p was diminished in tumor tissues of the EV group, and EVs by silencing NORAD could antagonize the trend." (PMID 35281474, 2022). "In a xenograft tumour model, radiation or NORAD knockdown alone did not change the TMB." (PMID 34587992, 2021). "Notably, although NORAD knockdown did not affect the volume of KYSE30/CDDP-R tumours, NORAD overexpression increased that of KYSE30 tumours." (PMID 34893064, 2021).
tumor (continued). "Meanwhile, no alteration occurred in tumor weight and volume of mice injected with PC cells that had been transfected with miR-202-5p mimic-NC, si-ANP32E-NC, ANP32E-NC, NORAD-NC and co-transfected with miR-202-5p mimic and ANP32E or NORAD and miR-202-5p mimic." (PMID 34551785, 2021). "A significant correlation was found between expression levels of NORAD and MAPK14 in tumor tissues but not in ANCTs." (PMID 32433496, 2020).
infection (2 papers, 2022 to 2025). The state of being infected such as from the introduction of a foreign agent such as serum, vaccine, antigenic substance or organism. "In contrast, lncRNAs LINC00278 and NORAD acquired novel m6A sites post-infection, suggesting a potential role for m6A in stress-induced activation or stabilization." (PMID 41267684, 2025). "Our analysis shows increased m6A methylation of GAS5, NORAD, and UCA1 during infection, pointing to further layers of post-transcriptional regulation." (PMID 41267684, 2025). "The expressions of lncRNAs UCA1, GAS5, NORAD, BISPR, and NEAT1 were quantified using Illumina cDNA (RNA-seq) sequencing data and compared to dRNA-seq using fold change expression in infection (normalized reads in infected/normalized reads in uninfected)." (PMID 41267684, 2025). "NORAD, THRIL, and GAS5 are involved in regulation of the NF-κB signaling pathway, a central axis of immune activation in response to respiratory viral infections and showed increased expression in infection." (PMID 41267684, 2025). "Infection of these cells with a genome-wide lentiviral CRISPR library followed by the identification of sgRNAs that were enriched in cells with diminished fluorescence enabled the discovery that RBM33, a poorly characterized RNA binding protein, is essential for NORAD nuclear export." (PMID 35589130, 2022).
bacterial infection (1 paper, 2023). "Other predicted lncRNAs (SNHG3, SNHG7, NORAD, AC023509.1, AC016876.2 and AC021078.1) can also be good subjects for further experimental tests to determine their exact role in bacterial infection and inflammation." (PMID 37169818, 2023).
degenerative diseases (1 paper, 2023). "Similarly, we determined that NORAD knockdown accelerates the senescence of irradiation-induced ARPE-19 and exacerbates the AMD phenotype, thereby further proving the close relationship between NORAD and aging degenerative diseases." (PMID 37517088, 2023). "Therefore, NORAD may be a good target for the treatment of degenerative diseases." (PMID 37517088, 2023).
neurological diseases (1 paper, 2024). "In addition, NORAD in humans encodes a lincRNA reported to inhibit vascular endothelial cell senescence and apoptosis and has a potential role in neurological diseases." (PMID 39156629, 2024).
NORAD also shares sentences with these, for which no sentence is quoted: glioblastoma (3 papers); colon carcinoma (2); papillary thyroid carcinoma (2); acute lung injury (1); Aortic dissection (1); autoimmune disease (1); breast neoplasm (1); cardiovascular diseases (1); diabetes (1); head and neck squamous cell carcinoma (1); hepatitis B (1); nasopharyngeal carcinoma (1); osteoporosis (1); prostate tumours (1); renal carcinoma (1); renal fibrosis (1); stomach adenocarcinoma (1).